TPM1 (tropomyosin 1)
Diseases named in the same sentence as TPM1 in open-access papers (continued):
Sharing a sentence is not in itself a finding about the gene and the disease.
hypertrophic cardiomyopathy (continued). "Notably, tropomyosin 1 (TPM1), myosin light chain 2 (MYL2), myosin heavy chain 11 (MYH11) and other DEPs were involved in hypertrophic cardiomyopathy, dilated cardiomyopathy and other pathways." (PMID 33785854, 2021). "Due to the relatively low number of detected down-regulated genes, only one pathway was found to be significant, and it contained genes overexpressed at the start of the training schedule (T1): hypertrophic cardiomyopathy (HCM) pathway (CACNB1, TPM1, TPM2, TTN)." (PMID 28381206, 2017).
dilated cardiomyopathy (24 papers, 2016 to 2026). Cardiomyopathy which is characterized by dilation and contractile dysfunction of the left and right ventricles. "Hypertrophic and dilated cardiomyopathy causing mutations have been detected mostly in genes of sarcomere proteins such as Mybpc2, Myh7, Tnnt2, Tnnc1, Tnni3, Tpm1, Ttn, Actc1, Myl2, and Myl3." (PMID 38981849, 2024). "Point mutations to the human gene TPM1 have been implicated in the development of both hypertrophic and dilated cardiomyopathies." (PMID 27833562, 2016). "TPM1 regulates the actin–myosin interaction, with important roles in cardiac muscle relaxation and contraction, and mutations in the Tpm1 gene lead to both hypertrophic and dilated cardiomyopathy." (PMID 35563680, 2022). "Indeed, in the heart, AS of exon 2b of TPM1 gene (Tropomyosin α 1) generates a splice variant associated with human dilated cardiomyopathy (DCM) and heart failure." (PMID 34205376, 2021). "It has been demonstrated that mutations in genes encoding cytoskeletal proteins, including tropomyosin 1 (TPM1) and myosin light chain 2 (MYL2), can cause dilated cardiomyopathy with impaired contractility and diastolic function." (PMID 33785854, 2021). "TPM1 plays a vital role in cardiogenesis and is closely related to a variety of CDs including inherited cardiomyopathy and dilated cardiomyopathy." (PMID 34975513, 2021). "The TPM1 AS events were discovered to be informative in prognostic predictors for head and neck cancer, dilated cardiomyopathy, and migration of esophageal cancer cells, demonstrating the functional diversity of TPM1 AS isoforms." (PMID 32175694, 2020). "TPM1-related dilated cardiomyopathy accounts for about 1% of DCM cases." (PMID 39684770, 2024). "The remaining pathways were all detected with a predominance of control proteins, such as the Citrate cycle (TCA cycle) (P-value < 0.0001; ACLY, DLST, PDHA1, PDHB), except Dilater cardiomyopathy (DCM) (P-value = 0.0006; ACTB, ADCY8, LOC396781, TPM1)." (PMID 38409238, 2024). "Dilated cardiomyopathy (DCM) pathway, including Lama2, Tnnt2, Actg1, Atp2a2, Gnas, Tpm3, Itga6, Tpm1, and Pln, was enriched in the KEGG pathway." (PMID 37858115, 2023).
bladder cancer (15 papers, 2014 to 2025). "Our study focuses on the prognostic, diagnostic, and therapeutic potential of miR-183-5p in bladder carcinoma and assess TPM1 gene targets and their modulatory functions." (PMID 41231336, 2025). "By characterizing miR-183-5p as an oncogenic promoter that downregulates TPM1, our work supports the concept of miRNA-based strategies as both diagnostic and therapeutic tools in bladder cancer." (PMID 41231336, 2025). "All these findings suggested that ACTA2, FLNA, TAGLN and TPM1 were potential diagnostic biomarkers for bladder cancer." (PMID 37274283, 2023). "TPM1 has been found to be a promising diagnostic and prognostic marker for bladder cancer." (PMID 35734544, 2022). "This study provides the first illustration of the miR-183-5p–TPM1 axis in bladder carcinoma, supporting the theranostic role of miR-183-5p as an onco-miR in BC progression, diagnosis, and prognostication." (PMID 41231336, 2025). "Additionally, integrating multi-omics analyses may reveal broader regulatory networks involving miR-183-5p and TPM1, and investigating combinatorial biomarker panels could enhance diagnostic precision, risk stratification, and therapeutic monitoring in bladder cancer." (PMID 41231336, 2025). "On the other hand, LncRNA-MEG3 is a miR-96 sponge in bladder cancer that adsorbs miR-96 expression and upregulates TPM1 expression, inhibits cell proliferation, delays the cell cycle, and promotes apoptosis." (PMID 37686101, 2023). "For example, in bladder cancer, TPM1 has a role in inhibiting bladder cancer cell proliferation and promoting apoptosis." (PMID 37686101, 2023). "Bioinformatic analyses demonstrated that the expression of ACTA2, FLNA, TAGLN and TPM1 in bladder cancer was markedly downregulated relative to nearby normal tissue." (PMID 37274283, 2023). "Next, we performed the survival analysis of these eight genes (ACTA2, CDH1, CCNB1, FLNA, MCM5, MAD2L1, TAGLN and TPM1) in bladder cancer." (PMID 37274283, 2023). "The high expression of TPM1 and TPM2 was associated with poor overall and disease-specific survival in bladder cancer patients (P < 0.05)." (PMID 35734544, 2022). "Meanwhile, according to previous studies, we found that TPM1,25SYNM,26CSRP1,27CFL2,28HIP1R29 are often found in the cancer genetic sequence of bladder cancer." (PMID 34541834, 2022). "The high expression of TPM1 and TPM2 is associated with poor overall and disease-specific survival in bladder cancer patients." (PMID 35734544, 2022). "The high expression of TPM1 and TPM2 is associated with poor overall and disease-specific survival in patients with bladder cancer (P < 0.05)." (PMID 35734544, 2022). "Cell experiments have confirmed that TPM1 inhibits the proliferation of bladder cancer cells and promotes cell apoptosis." (PMID 35734544, 2022). "In conclusion, TPM1 can be used as an effective marker to predict the survival and prognosis of bladder cancer patients." (PMID 35734544, 2022). "MEG3 overexpression has been shown to downregulate miR-96 while upregulating α-tropomyosin 1 (TPM1), which reduced bladder cancer cell viability by increasing apoptotic cell death." (PMID 36685879, 2022). "In bladder cancer and prostate cancer, TPM1 exon 6A and 6B are reported to have opposite splicing trends." (PMID 33563334, 2021). "Limitations and Future Directions: This study, through bioinformatic analysis, cellular experiments, and clinical correlation, strongly proposes the hypothesis that miR-183-5p plays a role in bladder cancer by targeting TPM1." (PMID 41231336, 2025). "According to current sequencing databases, no known mutational hotspots exist within the TPM1-4 genes in bladder cancer." (PMID 40937226, 2025). "By survival analysis, we found that their overall survival and disease-free survival curves also showed similarities, such as ACTA2 and TAGLN, FLNA and TPM1, suggesting that these genes have similar functions and are likely to be co-expressed and play a synergistic role in bladder cancer." (PMID 37274283, 2023).
bladder cancer (continued). "Subsequent studies have also shown that TPM1 may function as an anti‐oncogene to suppress many types of cancer development including gastric cancer, bladder carcinoma, lung cancer, and intrahepatic cholangiocarcinoma." (PMID 34850589, 2022). "TPM1 is an independent prognostic factor for bladder cancer." (PMID 35734544, 2022). "In addition to rediscovering previously known recurrent kinase fusions, we identified new fusion partners for many genes (for example, TPM1–ALK in bladder cancer, TBL1XR1–RET in thyroid cancer, and so on)." (PMID 25204415, 2014). "Therefore, we want to further analyze whether other genes in TM family are also a promising marker for bladder cancer diagnosis and prognosis as TPM1 has been reported in literatures." (PMID 35734544, 2022). "The results showed that TPM1 and TPM2 were significantly upregulated in bladder cancer, with log2 fold-change values of +1.76 and +1.71, respectively, and adjusted p-values < 1E-13, indicating robust statistical support." (PMID 40937226, 2025). "The expression levels of TPM1, TPM2, TPM3, and TPM4 in low grade bladder cancer were lower than those in high grade bladder cancer (P < 0.05)." (PMID 35734544, 2022). "A previous study, which found differential expression of the SYNM, TPM1, CSRP1 gene in bladder cancer, demonstrated the reliability of our study." (PMID 34541834, 2022). "The expression levels of TPM1, TPM2, TPM3, and TPM4 in low-grade bladder cancer were lower than those in high-grade bladder cancer." (PMID 35734544, 2022). "The results showed that TPM1 and TPM2 were positively correlated with macrophage and NK cell infiltration in bladder cancer." (PMID 35734544, 2022). "TPM1 and TPM2 are positively correlated with the infiltration of macrophages and NK cells in bladder cancer." (PMID 35734544, 2022). "Univariate analysis showed that age, TPM1, and TPM2 were prognostic factors for bladder cancer (P < 0.05)." (PMID 35734544, 2022). "We found that TPM1 and TPM2 were positively correlated with macrophage and NK cell infiltration in bladder cancer." (PMID 35734544, 2022). "MiR-21 and TPM1 expressions were analyzed by RT-qPCR and WB in 30 ESCC, 10 lung cancer, and 10 bladder cancer clinical specimens, each with matched adjacent normal tissue." (PMID 33193757, 2020). "The existing literature provides evidence that TPM1, TPM2, and TPM3 mRNA expression is altered in bladder cancer tissues and may be correlated with adverse clinical outcomes." (PMID 40937226, 2025). "The expression levels of TPM1, TPM2, and TPM4 genes were decreased in bladder cancer cells." (PMID 37686101, 2023). "Therefore, TPM1 and TPM2 are effective markers for the diagnosis of bladder cancer and are expected to be potential therapeutic targets for bladder cancer." (PMID 37686101, 2023). "TPM1 and TPM2 are effective markers for the diagnosis of bladder cancer." (PMID 35734544, 2022). "In addition, ROC curve indicated that TPM1, TPM2, and TPM3 had significant accuracy in the diagnosis of bladder cancer." (PMID 35734544, 2022). "Therefore, we infer that the low expression of TPM1, TPM2, and TPM4 is a mechanism of immunosuppression in bladder cancer." (PMID 35734544, 2022). "In conclusion, TPM1 and TPM2 are effective markers for the diagnosis of bladder cancer." (PMID 35734544, 2022). "Our study showed that TPM1, TPM2, and TPM4 were underexpressed in bladder cancer tissues." (PMID 35734544, 2022). "Therefore, TPM1, TPM2, and TPM3 are expected to be new markers for the diagnosis of bladder cancer and will play a potentially great value in clinical conversion application." (PMID 35734544, 2022). "It has been reported that TPM1 and TPM2 are highly expressed in normal urothelial tissues, but the expression of TPM1 and TPM2 is decreased in the early stage of bladder cancer, which may be a marker event of the occurrence and development of bladder cancer." (PMID 35734544, 2022).
bladder cancer (continued). "A recent study reported RNA interference studies in T24 and RT4 bladder cancer cell lines, suggesting that TPM1 knockdown may slightly enhance migration but does not significantly affect proliferation or apoptosis." (PMID 40937226, 2025). "It is worth noting that although TPM1 and TPM2 are highly expressed in normal urothelial tissues, the expression of TPM1 and TPM2 is decreased in the early stage of bladder cancer, which may be a marker event for the occurrence and development of bladder cancer." (PMID 37686101, 2023). "We have previously observed that TPM1, TPM2, and TPM4 are low expressed in bladder cancer, and therefore, the infiltration of NK cell, macrophages, neutrophils, and Th1 may be reduced accordingly in bladder cancer." (PMID 35734544, 2022). "Therefore, the low expression of TPM1, TPM2, and TPM4 in the tumor tissues of bladder cancer may be beneficial to the rapid proliferation of bladder cancer cells, indicating the development of bladder cancer." (PMID 35734544, 2022).
colorectal cancer (10 papers, 2009 to 2024). A primary or metastatic malignant neoplasm that affects the colon or rectum. "Down-regulation of TPM1 has been detected in both gastric and colorectal cancer during tumor invasion and lymph node metastasis, which are closely associated with BC progression, suggesting a role as tumor suppressor." (PMID 36131343, 2022). "For instance, under-expressed TPM1 was identified in colorectal cancer and TPM1 exerts inhibitory role development of colorectal cancer cells." (PMID 33653339, 2021). "Tropomyosin 1 (TPM1) plays an important role in lung cancer, colorectal cancer, and gastric cancer." (PMID 38790269, 2024). "In addition, the high expression level of TPM1 enhances the sensitivity of colorectal cancer cells to oxaliplatin via BCL-2 and BAX." (PMID 37854295, 2023). "TPM1 was found downregulated in colorectal cancer compared to normal tissue." (PMID 23213280, 2012).
gastric cancer (10 papers, 2015 to 2024). A primary or metastatic malignant neoplasm involving the stomach. "Similar findings were found that miRNA-183-5p.1 promotes the migration and invasion of gastric cancer AGS cells by targeting TPM1." (PMID 37686101, 2023). "TPM1-targeted miR-183-5p was able to lower the TPM1 expression in gastric cancer tissues and cell lines in comparison to that in the surrounding healthy tissues and gastric epithelial cells." (PMID 37174715, 2023). "Further studies revealed that ARHGAP11A promotes the malignant progression of gastric cancer cells by interacting with TPM1 to affect cell migration and invasion and the stability of actin filaments." (PMID 34912455, 2021). "Its function of regulating the stability of actin microfilaments and promoting the proliferation, invasion, and migration of gastric cancer cells depends on TPM1, thus promoting the malignant progression of gastric cancer." (PMID 34912455, 2021). "In summary, TPM1 is an interacting protein of ARHGAP11A that plays a key role in the ARHGAP11A-induced malignant progression of gastric cancer." (PMID 34912455, 2021). "Our study showed that ARHGAP11A can interact with TPM1 in gastric cancer cells, thereby promoting gastric cancer progression by affecting the formation and stability of the actin filaments." (PMID 34912455, 2021). "Low TPM1 expression predicted reduced survival in gastric cancer." (PMID 35477379, 2022). "It is reported that TPM1 is a new predictive biomarker for gastric cancer diagnosis and prognosis." (PMID 34912455, 2021). "As an oncogene in gastric cancer, ARHGAP11A is dependent on TPM1 to regulate cell stress fiber formation and stability and promote gastric cancer cell proliferation, invasion, and migration, thus promoting gastric cancer progression." (PMID 34912455, 2021). "Interestingly, in gastric carcinoma cells, miRNAs expressed by Epstein-Barr virus repress TPM1 and induce anchorage-independent growth suggesting that down-regulation of TPM1 by viral-miRNAs could be a general mechanism used by herpesviruses to inhibit anoikis." (PMID 26263384, 2015).
prostate carcinoma (10 papers, 2021 to 2024). A carcinoma that arises from epithelial cells of the prostate gland. "Recently, it has been found that m6A modification of TPM1 can promote the therapeutic efficacy of prostate cancer by mediating m6A modification, which affects the expression level of mRNA by affecting its shearing and translation." (PMID 38790269, 2024). "A core network consisting of 19 genes was identified, and most genes in the core network have been reported to play important roles in prostate cancer, especially TPM1, ITGB3, and CALD1." (PMID 38778150, 2024). "The downregulation of TPM1 enhanced prostate cancer cell proliferation, invasion and migration via cell-derived exosomal miR-183 in prostate cancer." (PMID 34116652, 2021). "Previous well-established evidence has indicated the role of exosomal miR-183 as a contributor to cell proliferation and metastasis in prostate cancer with the involvement of TPM1." (PMID 33653339, 2021). "Taken together, the key findings of the present study collectively evidence that exosomal miR-183 derived from PC3 cells facilitates prostate cancer LNCaP cell proliferation, migration, and invasion via downregulating TPM1." (PMID 33653339, 2021). "A key observation made during the current study indicated that TPM1 as a tumor suppressor gene was poorly expressed in prostate cancer cells." (PMID 33653339, 2021). "The putative target gene TPM1 of miR-183 was subsequently predicted, followed by the application of a luciferase reporter assay and examination of the expression patterns in prostate cancer patients and cell lines." (PMID 33653339, 2021). "Moreover, miR-183 has been reported to be differentially expressed and capable of targeting TPM1 in prostate cancer was verified in our study." (PMID 33653339, 2021). "Hence, we asserted the notion that miR-183 contributes to the metastatic progression of prostate cancer cells by targeting TPM1." (PMID 33653339, 2021). "Our data indicated that miR-183 could target and downregulate TPM1, with the overexpression of miR-183 and exosomal miR-183 found to promote cell proliferation, migration, and invasion in prostate cancer." (PMID 33653339, 2021). "High expression of miR-183 accompanied with low expression of TPM1 was detected in prostate cancer." (PMID 33653339, 2021). "Accordingly, we considered the possibility that miR-183 may contribute to tumor growth and metastasis acceleration in prostate cancer via the downregulation of TPM1." (PMID 33653339, 2021). "Furthermore, the inhibition of exosomal miR-183 was found to impede cell proliferation, migration, and invasion in prostate cancer through the upregulation of TPM1." (PMID 33653339, 2021). "Taken together, the key findings of our study demonstrate that prostate cancer cell-derived exosomal miR-183 enhance prostate cancer cell proliferation, invasion and migration via the downregulation of TPM1, highlighting a promising therapeutic target against prostate cancer." (PMID 33653339, 2021). "Network analysis was performed on the intersection of 300 genes from these six datasets, and qRT-PCR validation confirmed the 3 top hub genes (TPM1, ITGB3, and CALD1) in the network are expression in prostate cancer tissues." (PMID 38778150, 2024). "In contrast to miR183 expression, the expression of TPM1 in prostate cancer was distinctly lower than that in the normal samples from the GEPIA database, supporting our earlier in silico prediction." (PMID 33653339, 2021).